CDK6 (cyclin dependent kinase 6)
Diseases named in the same sentence as CDK6 in open-access papers (continued):
Sharing a sentence is not in itself a finding about the gene and the disease.
lymphoma (34 papers, 2008 to 2025). A malignant (clonal) proliferation of B- lymphocytes or T- lymphocytes which involves the lymph nodes, bone marrow and/or extranodal sites. "Hypo-methylation of CDK6 is associated with T cell dysfunctional phenotype high death risk and low survival duration in lymphoma, cervical, and brain cancer patients." (PMID 33668805, 2021). "Combination therapies based upon vorinostat and 3-deazaneplanocin resulted in lymphoma growth suppression in vitro and in vivo and restored miR-29 expression, thus leading to inhibition of the lymphoma-associated miR-29 targets, CDK6 and IGF1R." (PMID 25968566, 2015). "CDK6 has also been implicated in thymic lymphoma formation in a transgenic mouse model in which lymphoma development is triggered by a constitutively active AKT." (PMID 23948297, 2013). "Similarly, overexpression of the human RB kinase CDK6 is associated with sporadic cases of lymphoma." (PMID 27015111, 2016). "CDK6 was shown to be a key regulator of the G1-S phase cell cycle transition and its inhibition induced apoptosis in T-cell leukemia/lymphoma." (PMID 37624039, 2023). "Interesting, YY1 and CDK6 have been demonstrated as direct targets of miR-29 by the reporter assay in rhabdomyosarcoma and lymphoma." (PMID 35628336, 2022). "Accordingly, simultaneous inhibition of the mTOR pathway and CDK6 activity by palbociclib exerted greater antitumor activity than either treatment alone, both in vitro in human T cell acute lymphoblastic leukemia/lymphoma and in vivo." (PMID 34439268, 2021). "PTEN, CDK6, CCNDs, RB, and dominant-negative Ikaros isoform expression has been previously shown to be altered in human T-cell leukemias/lymphomas." (PMID 25452272, 2014). "For example, in lymphoma CDK6 induces the transcription of growth factors such as Vegf-A. Although tumor growth depends on angiogenesis, there are few indications of factors involved in the regulation of both processes." (PMID 23948297, 2013). "To investigate the consequences of increasing CDK6 expression in B-lymphoid leukemia/lymphoma, we generated stable p185BCR-ABL-transformed pro B cell lines." (PMID 23948297, 2013). "As CDK6 participates in cell cycle dysregulation in many solid tumors and lymphoma, there is a potential benefit of CDK4/6 inhibitors for the treatment of these tumors; however, de novo or acquired treatment resistance has also been reported in several tumor models." (PMID 35463324, 2022). "In cell lines derived from NPM-ALK+Cdk6+/+ lymphomas, we found pronounced high CDK6 protein levels." (PMID 23948297, 2013). "Noticeably, amplification of CDK6 has been recently described in lymphoma." (PMID 18925961, 2008). "Multiple factors, such as EZH2, c-MYC, IKZF1, IKZF3, IRF4, and CDK6, which are essential for the proliferation and survival of malignant plasma cells and lymphoma, were decreased upon treatment with PM in all tested MM and lymphoma cell lines, including MM1S, MM1R, and TMD-8." (PMID 40562746, 2025). "Virus-positive cells also demonstrated increased sensitivities to Palbociclib compared to virus-negative BJAB cells, which was consistent with previous reports and suggested that CDK4/CDK6 may have additional functions to support the survival and proliferation of virus-transformed lymphoma cells." (PMID 38365882, 2024). "CDK6 is the initial CDK induced during T-lymphocyte activation/proliferation and is highly expressed in T-cell lymphoblastic leukemias/lymphomas; similarly, over-expression of cyclin D3 is oncogenic in an array of mouse and human T-ALL cell lines." (PMID 22514694, 2012). "It has been confirmed that CDK4 and CDK6 are closely related to tumorigenesis, and inhibition of CDK4/6 could bring an anti-tumor effect in several tumors, including lymphoma." (PMID 38589831, 2024). "In lymphoma cells, miR-29 could target 3’ UTR of CDK6 and modulate the cell cycle G1/S transition and cell proliferation." (PMID 37814227, 2023).
lymphoma (continued). "CDK6 was found to be uniformly overexpressed in T-cell leukemia/lymphoma in the absence of gene amplification, and higher expression of CDK6 but not CDK4 was observed in B-ALL cells in comparison to normal bone marrow cells." (PMID 34573335, 2021). "In this particular setting, lymphomas did not develop in the absence of CDK6." (PMID 23948297, 2013).
medulloblastoma (31 papers, 2010 to 2026). A malignant, invasive embryonal neoplasm arising from the cerebellum. "A recent study showed the association between cyclin dependent kinase 6 (CDK6) and miR-124 in medulloblastoma cell lines." (PMID 20975961, 2010). "Treating SHH medulloblastoma cells with a miR-449a mimic led to a marked decrease in CDK6 protein expression." (PMID 40495204, 2025). "In a high-throughput drug screen, BRD4 inhibitors have been found to be one of the two classes of compounds exerting the best synergistic anticancer effects with the CDK4/CDK6 inhibitor Ribociclib in medulloblastoma cells." (PMID 38135679, 2023). "A reverse combination drug screen identifies CDK4/CDK6 inhibitors as the compounds exerting the best synergy with the BRD4 inhibitor JQ1 against medulloblastoma cells." (PMID 38135679, 2023). "Adults make for difficult patients to treat as their medulloblastoma genomic profiles are very different in adult medulloblastomas and there is a connection between the amplification of CDK6 and rapidly terminal outcomes." (PMID 35481313, 2022). "CDK6 has been reported in many solid tumours, such as colorectal carcinoma, medulloblastoma and oral squamous cell carcinomas." (PMID 33586348, 2021). "In the analysis of a large group of pediatric embryonal brain tumors including medulloblastoma and supratentorial neuroectodermal tumor (sPNET), CDK6 and CCND1 gene amplification are more commonly observed in sPNET (25%)." (PMID 29416789, 2018). "They found that miR-124 inhibits cell proliferation in vitro and xenograft tumor growth in vivo of medulloblastoma cells by targeting cyclin-dependent kinase 6 (CDK6)." (PMID 25928665, 2015). "Furthermore, consistent with the growth arrest of the cells in the G0/G1 phase, the expression of p16, a CDK4/CDK6 inhibitor, was found to be upregulated in medulloblastoma cells upon miR-193a expression." (PMID 32410663, 2020). "Cdk6 is a direct transcriptional target of the Hedgehog pathway, which regulates the G1-S transition of the cell cycle and its aberrant expression in human medulloblastomas has been correlated with poor prognosis." (PMID 25901736, 2015). "Furthermore, overexpression of CDK6 is correlated with poor prognosis and might be a molecular marker for the prognostic assessment of medulloblastoma." (PMID 30530570, 2019). "Group 4 is the most prevalent group comprising 43% of all medulloblastomas and can be subdivided into three subgroups: Group 4α, characterized by MYCN amplification; Group 4β by CNCAIP duplication and Group 4γ by CDK6 amplification." (PMID 30279357, 2018). "Thus, CDK6 antagonists may represent a promising therapeutic approach for MBSHH medulloblastomas." (PMID 30279357, 2018). "Cyclin dependent kinase 6 (CDK6) and Solute Carrier Family 16 (SLC16A1) are two identified key targets of miRNA-124 in Medulloblastoma, suggesting a role for this miRNA in cell proliferation and cell cycle." (PMID 29073265, 2017). "Silencing miR-1253 targets CDK6 and CD276 to suppress the growth of medulloblastoma." (PMID 35464451, 2022). "Specifically, miR-124a was previously reported as a regulator of CDK6 in GBM and medulloblastoma." (PMID 21358821, 2011). "High expressions of CDK6 and CD276 have a negative influence on medulloblastoma survival, meaning that they play pro-oncogenic roles in medulloblastoma, supporting similar findings from prior studies." (PMID 35464451, 2022). "Therefore, given the functional importance of CDK6 in regulating the growth of SHH-medulloblastoma cells, we transfected SHH-DAOY cells with miR-449a mimic or non-functional (negative control miRNA mimic) miRNAs, and measured CDK6 protein expression 72 h post-treatment." (PMID 40495204, 2025).
osteosarcoma (30 papers, 2011 to 2025). A usually aggressive malignant bone-forming mesenchymal neoplasm, predominantly affecting adolescents and young adults. "Notably, this research revealed a therapeutic opportunity: CDK4/CDK6 inhibitors, like palbociclib, effectively target p16INK4A loss in osteosarcoma models." (PMID 40563473, 2025). "Another subgroup of osteosarcoma patients that might benefit from CDK4/CDK6 inhibition, include patients with intact Rb, but loss of p16 expression." (PMID 34921235, 2022). "Interestingly, about half of the osteosarcoma patients (44.8%) showed overexpression of CDK6 which was associated with a worse overall survival." (PMID 34921235, 2022). "Taken together, our results illustrate that there is a clear subset of osteosarcoma patients (20–23%) for which CDK4/CDK6 inhibition might be promising and that loss of p16 protein expression or overexpression of CDK6, combined with intact Rb, may serve as a biomarker to select eligible patients." (PMID 34921235, 2022). "MiR-524-5p induces apoptosis in osteosarcoma cells by targeting and inhibiting Cyclin-Dependent Kinase 6 (CDK6)." (PMID 39419925, 2025). "MiR-3928, targeting ERBB3, IL-6R, and CDK6, leads to an increase in G1 phase cells and a decrease in S-phase cells, suggesting its possible therapeutic potential to fight osteosarcoma." (PMID 39419925, 2025). "Mechanically, circPRMT5 promoted the binding of CNBP to CDK6 mRNA, which enhanced the stability of CDK6 mRNA and facilitated its translation, thereby promoting the progression of osteosarcoma." (PMID 38626179, 2024). "Mechanistically, circPRMT5 enhanced cyclin-dependent kinase 6 (CDK6) expression by promoting the binding of CCHC-type zinc finger nucleic acid binding protein (CNBP) to CDK6 mRNA in osteosarcoma cells." (PMID 38626179, 2024). "Our study suggests that circPRMT5 promotes the malignant activity of osteosarcoma cells by promoting CDK6 expression, and inhibition of CDK6 expression can reverse these stimulative effects." (PMID 38626179, 2024). "Together, these findings indicated that circPRMT5 promoted osteosarcoma cell malignant activity by upregulating CDK6 expression." (PMID 38626179, 2024). "Lastly, the drug sensitivity data from Genomics of Drug Sensitivity in Cancer (GDSC, version 17.3) showed osteosarcoma cell lines with various response to CDK6 or EGFR inhibitors." (PMID 37894336, 2023). "This is in line with other in vitro studies showing that pan-CDK or specific CDK4/CDK6 inhibition in osteosarcoma resulted in growth inhibition of cells and increased senescence and/or apoptosis." (PMID 34921235, 2022). "As the efficacy of CDK4/CDK6 inhibition relies on the presence of intact Rb, the Rb status of each osteosarcoma cell line was determined by Western blot." (PMID 34921235, 2022). "Our study demonstrates that 20–23% of primary osteosarcoma biopsies showed intact Rb, but defective p16 INK4A or overexpression of CDK4 and/or CDK6, indicating potential benefit from CDK4/CDK6 inhibition in almost one quarter of osteosarcoma patients." (PMID 34921235, 2022). "CDK4 is amplified in 10% of high-grade osteosarcomas, and together with CDK6 directly controls Rb activity by phosphorylation of Rb7–9." (PMID 34921235, 2022). "MSC-AS1 was found to regulate the tumor progression by inhibiting miR-124 expression to increase CDK6 expression in osteosarcoma." (PMID 34054957, 2021). "The LOC100129620/miR-335-3p/CDK6 signaling pathway promotes the metastasis of osteosarcoma by regulating the proliferation of osteosarcoma cells, angiogenesis, and macrophage polarization." (PMID 34015762, 2021). "In this study, we found that LOC100129620 promotes the proliferation, migration, and invasion of osteosarcoma cells through the LOC100129620/miR-335-3p/CDK6 signaling axis." (PMID 34015762, 2021).
osteosarcoma (continued). "Here, we detected upregulation of CDK4 and/or CDK6 mRNA levels in all osteosarcomas, which suggests a predominant mechanism of RB-E2F pathway inactivation through RB hyperphosphorylation in this malignancy." (PMID 30220967, 2018). "CDK4 and CDK6 amplification and overexpression has been reported in some osteosarcomas, resulting in RB hyperphosphorylation." (PMID 30220967, 2018). "To investigate the underlying molecular mechanism of baicalein on cell cycle regulation, we examined the expression levels of Cyclin D1, Cyclin E1, CDK4, CDK6, c-myc, pRb, p21 and p27 in osteosarcoma cells, which treated with different doses of baicalein." (PMID 29156780, 2017). "The inverse correlation between miR-29b and CDK6 expression level in osteosarcoma tissues and normal adjacent tissues was further analyzed." (PMID 27230400, 2016). "In this study, we found that overexpressing miR-29b can inhibit proliferation and migration of osteosarcoma cells and that CDK6 reduction can mimic the effect of miR-29b induction." (PMID 27230400, 2016). "In conclusion, our results demonstrated that miR-29b directly recognizes and binds to the 3′-UTR of the CDK6 mRNA transcript and inhibits CDK6 translation in osteosarcoma cells." (PMID 27230400, 2016). "The results revealed that the inverse correlation of miR-29b with the CDK6 protein was stronger than that with the CDK6 mRNA in the osteosarcoma tissues." (PMID 27230400, 2016). "Our studies reveal the importance of miR-29b targeting CDK6 as a novel regulatory pathway in osteosarcoma progression." (PMID 27230400, 2016). "The correlation between miR-29b and CDK6 was further examined by evaluating CDK6 expression in the human osteosarcoma cell line MG-63 after overexpression of miR-29b." (PMID 27230400, 2016). "This disparity between CDK6 protein and mRNA levels in osteosarcoma tissues strongly suggest that a post-transcriptional mechanism is involved in the regulation of CDK6." (PMID 27230400, 2016). "Both miR-449a and miR-449b were first described as tumor suppressors in osteosarcoma cells, targeting CDK6 and CDC25A." (PMID 26934316, 2016). "We demonstrated that CDK6 can be downregulated by miR-29b via binding to the 3′-UTR region in osteosarcoma cells." (PMID 27230400, 2016). "The results revealed that miR-29b acts as a tumor suppressor of osteosarcoma by targeting CDK6 in the proliferation and migration processes." (PMID 27230400, 2016). "Taken as a whole, this study delineates a novel regulatory network employing miR-29b and CDK6 to regulate proliferation and migration in osteosarcoma cells." (PMID 27230400, 2016). "Subsequently, we investigated the role of CDK6 on cell proliferation by overexpression or knockdown of CDK6 to provide a better understanding of the CDK6-involved pathway in osteosarcoma." (PMID 27230400, 2016). "We next analyzed the biological consequences of the miR-29b-driven repression of CDK6 expression in osteosarcoma cells." (PMID 27230400, 2016). "To examine whether the function role of circPRMT5 in promoting the malignant activity of osteosarcoma cells involves CDK6, we performed rescue experiments." (PMID 38626179, 2024). "Knockdown of CDK6 reversed the promoting effect of circPRMT5 on osteosarcoma cells." (PMID 38626179, 2024). "Together, these findings indicate that circPRMT5 may serve as an oncogenic factor to promote CNBP-facilitated CDK6 expression and osteosarcoma progression." (PMID 38626179, 2024). "The Akt pathway is related to the expression of cyclin D1 and CDK6 in osteosarcoma." (PMID 38130464, 2023). "BAMBI has also been reported to regulate cyclin D1, CDK2, and CDK6 in human osteosarcoma cells." (PMID 36109807, 2022). "This can be exploited with a CDK4/CDK6 inhibitor, as osteosarcoma cells showed sensitivity to palbociclib which might be used as a novel therapeutic option." (PMID 34921235, 2022). "Therefore, we investigated the sensitivity to CDK4/CDK6 inhibitor palbociclib in osteosarcoma cells." (PMID 34921235, 2022).